CCL2 (C-C motif chemokine ligand 2)
Diseases named in the same sentence as CCL2 in open-access papers (continued):
Sharing a sentence is not in itself a finding about the gene and the disease.
sarcoidosis (21 papers, 2005 to 2025). Sarcoidosis is a multisystemic disorder of unknown cause characterized by the formation of immune granulomas in involved organs. "IL1-β, TNF and IL-6 are all fundamentally associated with sarcoidosis, and CCL2 is a potent chemotactic agent for monocytes and T cells, and is strongly increased in BAL fluid of sarcoidosis patients." (PMID 32948789, 2020). "These were: Th1 cytokine INFG, which mRNA and protein was elevated in Th1 polarised sarcoidosis and CC chemokine ligand (CCL)-2/MCP-1, implicated in the development of sarcoid alveolitis namely in chest X-ray stage 2 disease." (PMID 18671841, 2008). "However, in the final analysis we focused on Fibronectin 1 (FN1) and Chemokine (C-C motif) ligand 2 (CCL2) that had the strongest associations to sarcoidosis in both sample sets." (PMID 27259755, 2016). "In order to demonstrate the effect of used reference genes on the result of target gene expression data in BAL cells, we investigated relative mRNA expression of two cytokines known to be associated with sarcoidosis, INFG and CCL2, in sarcoidosis patients and control subjects (2nd cohort)." (PMID 18671841, 2008). "The levels of MCP-1 (CCl2) were significantly higher in amiodarone lung patients than in sarcoidosis patients (p < 0.0001)." (PMID 40725075, 2025). "Sarcoidosis fibroblasts also produced increased levels of chemoattractants (CCL2, CCL4, CCL5, CXCL9), suggesting a role in both maintaining T cell activation as well as in recruiting monocytes and T cells to the tissue microenvironment." (PMID 35668129, 2022). "The CCL2 induction and Montelukast effect seemed most prominent in a subgroup of patients with more Lofgren`s syndrome (LS, an acute form of sarcoidosis) and possibly those receiving NSAID treatment." (PMID 32948789, 2020). "Although the BAL fluid levels of both FN1 and CCL2 were increased in sarcoidosis patients compared to both healthy and diseased controls, the levels of these two proteins were more similar between the two subtypes of disease, i.e., in LS and non-LS patients." (PMID 27259755, 2016). "We found increased levels of CCL2 in BAL fluid of sarcoidosis patients compared to controls, which is in line with previous studies although there are contradictory reports as well." (PMID 27259755, 2016). "Overall, the evidence for elevated CCL2 in human sarcoidosis and in MWCNT-instilled wild-type and PPARγ KO mice suggests that this chemokine is an important element of inflammatory pulmonary granuloma formation." (PMID 23343389, 2013). "The BALF protein levels of CCL2 were significantly higher in sarcoidosis patients as compared to controls." (PMID 21463523, 2011). "Using genes PSMB2 (1.95 ± 1.66; p = 0.02) and gene RPL32 (1.77 ± 1.25; p = 0.03), and gene pair PSMB2-RPL32 (1.65 ± 1.17; p = 0.02) as denominators, CCL2 mRNA levels differed between chest radiographic stage 2 and stage 1 sarcoidosis patients." (PMID 18671841, 2008). "Additionally, exosomes from the broncho alveolar lavage fluid (BALF) of sarcoidosis patients can induce the expression of CCL2 (MCP1)." (PMID 34135893, 2021). "It has been speculated that exosomes are mediators and disseminators of inflammation, opening the way for further investigations of the link between CCL2 and exosomal leukotrienes in sarcoidosis." (PMID 34947932, 2021). "Gene expression analyses in both MWCNT-instilled mice and sarcoidosis indicated a multitude of elevated inflammatory mediators that may modify CCL2 effects." (PMID 33072094, 2020). "The monocyte/macrophage chemokine CCL2 has been linked to granuloma formation in other animal model systems and transcriptional studies also indicated elevated expression in both MWCNT instilled mice and sarcoidosis patients." (PMID 33072094, 2020). "ROC analysis was applied to the data to evaluate how well the levels of FN1 and CCL2 could classify sarcoidosis patients from controls." (PMID 27259755, 2016).
sarcoidosis (continued). "Finally, we demonstrated on the example of INFG and CCL2 mRNA expression in sarcoidosis that the normalisation with validated reference genes in clinical samples is absolute prerequisite for obtaining clinically meaningful information from qRT-PCR." (PMID 18671841, 2008). "Therefore, our observations that Montelukast can reduce CCL2 for at least a subgroup of sarcoidosis patients may have its explanation in a combination of heterogeneity in Montelukast efficacy, patient differences and the complex nature of exosomes." (PMID 32948789, 2020). "Interestingly, elevated CCL2 is also present in sarcoidosis BAL cells and fluids as well as serum." (PMID 23343389, 2013). "For approximately half of the 30 sarcoidosis BALF exosome stimulations, the CCL2 levels were decreased by Montelukast." (PMID 32948789, 2020). "Corresponding classification analysis of the two clinical subtypes of sarcoidosis revealed AUC values of 0.5 for FN1 and 0.6 for CCL2, illustrating the similarity in protein levels between the two subtypes of disease." (PMID 27259755, 2016). "The two proteins with highest significance were fibronectin 1 (FN1, HPA027066) and C-C motif chemokine 2 (CCL2, HPA019163) with higher levels in the sarcoidosis group compared to the healthy controls (p < 0.001 in both sample sets)." (PMID 27259755, 2016). "Similar, when CCL2 mRNA levels were expressed as a ratio to ACTB (1.00 ± 0.85; p = 0.46) or to GAPDH (1.37 ± 0.98; p = 0.43), there were not significant differences in mRNA levels in BAL cells between sarcoidosis patients with chest radiographic stage 2 and stage 1 patients." (PMID 18671841, 2008).
delirium (20 papers, 2011 to 2026). A disorder characterized by confusion; inattentiveness; disorientation; illusions; hallucinations; agitation; and in some instances autonomic nervous system overactivity. "Delirium resolution was characterized by normalization of key transcripts such as CCL2 and innate immune markers." (PMID 40982210, 2025). "IL-6, IL-8, IL-10, IL-18, TNF-α, and chemokines (CCL2, CCL3, CXCL1, and CXCL10) have also been reported to be elevated in ICU delirium patients and are associated with delirium severity." (PMID 39308447, 2024). "Some research has indicated a potential connection between blood CCL2 and delirium." (PMID 38861234, 2025). "CCL2 (also known as MCP-1) is elevated immediately after surgery in patients with delirium." (PMID 37759795, 2023). "LM‐ and AS‐induced delirium led to microglial activation in the hippocampus as evidenced by up‐regulation of microglial activation‐related genes (such as Il6ra, Tyrobp, Cd68, Aif1, Csf1r, and Trem2) and of relevant inflammatory factors (such as Il‐1β, Tnfα, Ccl2, Ccl5, and Ccl8)." (PMID 35713240, 2022). "However, there are no data whether delirium is associated with M1 macrophage, Th1, Th2, Th17, Treg or CIRS cytokine profiles, and whether a neurotoxic cytokine profile including M1, Th1, Th17 and neurotoxic chemokines, such as CCL11, CCL2, CCL3, CCL5, and CXCL10) is associated with delirium." (PMID 35641947, 2022).
Hyperinsulinemia (20 papers, 2010 to 2025). An increased concentration of insulin in the blood. "In particular, CCL2 may contribute to pathologies associated with hyperinsulinemia, given that ccl2 is an insulin-responsive gene that may alter adipocyte function." (PMID 20936118, 2010). "Changes in metabolic parameters occurred as early as 6-weeks in DIO mice as evidenced by hyperinsulinemia, increased leptin levels and modestly increased levels of pro-inflammatory mediators, including CCL2 and IL-6, in the serum and in the EF pad." (PMID 20445733, 2010). "Rosiglitazone treatment reduced hyperinsulinemia (DIO 4510 +/− 490 pg/ml: DIO-Rosi 2170 +/− 620 pg/ml), serum CCL2 levels (DIO 84.2 +/− 0.18 pg/ml: DIO-Rosi 47.3 +/− 4.6 pg/ml) and SVF mediator production of IL-6, TNFα, IL-1β and IL-10." (PMID 20445733, 2010).
infarction (20 papers, 2011 to 2025). A localised pathological necrosis of tissue resulting from obstruction of the blood supply usually by a thrombus, an embolus, or vascular torsion. "As research continues to ascend,persistent high expression of CCL2 in HF animal experiments, with or withoutmyocardial infarction, is closely associated with myocardial dysfunction,fibrosis, and ultimately cardiac remodeling." (PMID 39077559, 2023). "Monocytes/macrophages are recruited via CCL2/CCR2 axis, and deletion of CCR2 or CCL2 results in smaller cerebral infarcts, reduced monocytes/macrophages infiltration, and less proinflammatory mediator production, indicating a deleterious effect of these cells." (PMID 24877133, 2014).
Infertility (20 papers, 2012 to 2025). "Indeed, a recent MR study by our group demonstrated a positive causal association between MCP-1/CCL2 and anovulatory infertility (unpublished)." (PMID 39766252, 2024). "Finally, a cohort of infertile men with a history of MetS showed that reduction of CCL2 plasma levels could be achieved by weight loss and was clearly associated with recovery from hypogonadism." (PMID 33148888, 2020). "Our reports of causal links between MCP-1/CCL2 and both PCOS and anovulatory infertility are of clinical relevance because PCOS is the most common cause of anovulation and the leading cause of infertility globally." (PMID 39766252, 2024).
peripheral nerve injury (20 papers, 2011 to 2025). Injury to a peripheral nerve. "In addition, Ccl2 can promote the polarization of M2‐type macrophages and enhance the growth of axons in peripheral nerve injury." (PMID 36047918, 2022). "Moreover, the CCL2-mediated neuron-macrophage interaction is vital for amplification and maintenance of enhanced regenerative capacity by preconditioning peripheral nerve injury." (PMID 27717377, 2016). "Like NIS-lncRNA, Ccl2 mRNA and CCL2 protein were significantly increased predominantly in large and medium neurons of injured DRG after peripheral nerve injury." (PMID 35775484, 2022). "Consistent with that possibility, the chemokines CCL2, CCL3, and CX3CL1 are all highly expressed after peripheral nerve injury with the corresponding chemokine receptors, CCR2, CCR5, and CX3CR1 expressed by NK cells." (PMID 30712871, 2019). "CCL2/CCR2-mediated NMDAR activity in D1R- and D2R-containing neurons after peripheral nerve injury." (PMID 37860084, 2023). "Our research is the first comprehensive behavioral and biochemical study showing that many endogenous ligands of CCR1 (CCL2/3/5/7/8/9) and CCR3 (CCL5/7/8) are significant in the development (CCL2/3/5/7/8/9) and maintenance (CCL2/7/8) of neuropathic pain after peripheral nerve injury in mice." (PMID 36611891, 2022). "Chemokine (C-C motif) ligand 2 (CCL2), also known as monocyte chemoattractant protein 1 (MCP-1), produced by primary afferent neurons in the spinal dorsal horn, is released in synaptic vesicles following peripheral nerve injury." (PMID 33183347, 2020). "Given that NIS-lncRNA also bound to R7 of the Ccl2 gene promoter, the evidence indicates that NIS-lncRNA may function as a molecular scaffolder to recruit FUS to the Ccl2 gene promoter to trigger its transcription in injured DRGs after peripheral nerve injury." (PMID 35775484, 2022).
age-related macular degeneration (19 papers, 2010 to 2023). Age-related loss of vision in the central portion of the retina (macula), secondary to retinal degeneration. "Our SNP studies with patients of age related macular degeneration (AMD) showed higher frequency of TT genotype of CCL2 gene." (PMID 24847438, 2014). "Furthermore, aqueous samples from eyes with advanced exudative age-related macular degeneration contain higher levels of CCL2 compared with age-matched controls and CCL2 is increased with normal ageing in the RPE/choroidal complex of aged C57Bl/6 mice." (PMID 23232206, 2013). "In the retina, upregulation of α and β chemokines, such as Ccl2, Cxcl1, and Cxcl10 have been detected by gene expression analyses in both wet and dry forms of age-related macular degeneration (AMD)." (PMID 25595590, 2015). "Defining the role of Ccl2-Ccr2 and Cx3cl1-Cx3cr1 signalling for retinal pathology is of particular interest because of its potential role in age-related macular degeneration (AMD)." (PMID 22545116, 2012).
autism (19 papers, 2011 to 2025). Persistent deficits in social interaction and communication and interaction as well as a markedly restricted repertoire of activity and interest as well as repetitive patterns of behavior. "Neuroimmune biomarkers linked to autism and/or pioglitazone, namely, IL-6, tumor necrosis factor (TNF)-alpha, monocyte chemotactic protein (MCP)-1/CCL2, insulin, and leptin, were also studied." (PMID 29791472, 2018).
chronic obstructive pulmonary disease (19 papers, 2015 to 2025). A chronic and progressive lung disorder characterized by the loss of elasticity of the bronchial tree and the air sacs, destruction of the air sacs wall, thickening of the bronchial wall, and mucous accumulation in the bronchial tree. "In the Chinese population, the minor T allele in CCL2 rs4586 was found to be associated with significantly elevated serum CCL2 levels, which also correlated with a higher risk of chronic obstructive pulmonary disease." (PMID 38001676, 2023). "For example, decreased expression of the ARE binding protein AUF-1 in chronic obstructive pulmonary disease (COPD) patient samples leads to stabilization of IL-6, CCL2, CCL1 and CXCL8 mRNA." (PMID 33806254, 2021). "The CCR2 ligand CCL2, produced by bronchial epithelial cells, is increased in the sputum of chronic obstructive pulmonary disease (COPD) patients and recent data in CCL2 knock‐out mice supports an important role of the CCL2‐CCR2 axis in the development of lung emphysema." (PMID 40432300, 2025).
Crohn disease (19 papers, 2009 to 2025). A gastrointestinal disorder characterized by chronic inflammation involving all layers of the intestinal wall, noncaseating granulomas affecting the intestinal wall and regional lymph nodes, and transmural fibrosis. "Chemokines implicated in Crohns disease are numerous, some includes CCL2, 4, 5, 8 and 20, and CXCL1, 2, 3, 8, 10, which are expressed by several of our cocktail treated DCs." (PMID 20663192, 2010). "Of especial interest is the recent description of an MCP-1 (CCL2) polymorphism that is associated with Crohn's disease, which may have implications for disease pathogenesis." (PMID 21806815, 2011). "As an example, the -2518A/G variation within the CCL2 promotor region has been shown to be associated with Crohn’s disease without affecting CCL2 plasma levels." (PMID 33540898, 2021). "Fifth, It has been demonstrated recently that VSL#3 up- or downregulates the expression of several genes related to immunomodulation and inflammation, including the expression of the proinflammatory chemokine MCP-1/CCL2 in macrophages of children affected by Crohn disease." (PMID 23691109, 2013). "Reconciling observations in chronic intestinal inflammation, where CCL2 is increased in both UC and CD, and changes in fibronectin expression, which appears to only undergo an increase in UC (and fibrotic Crohn's disease), is not straightforward." (PMID 21806815, 2011).
kidney injury (19 papers, 2013 to 2025). Trauma to the kidney. "In particular, Serpinb2 has been reported to link to the enhancement of CCL2 expression and the regulation of macrophage function in the context of kidney injury." (PMID 40485847, 2025). "Interestingly, some of the drivers for group separation (i.e., Tnfa, Ccl2, Il6, Lcn2, and UACR) were not significantly different between any of the four mouse groups when analyzed in isolation, but are widely known indicators of kidney injury." (PMID 34835482, 2021).
macular edema (19 papers, 2012 to 2025). "MCP-1 (CCL2) is consistently increased in aqueous and vitreous samples from patients with DR and correlates with macular edema." (PMID 35941655, 2022). "High levels of CCL2 are present in diabetic patients with proliferative DR and macular oedema." (PMID 38203187, 2023).
migraine (19 papers, 2013 to 2024). "The proinflammatory cytokine CCL2 is implicated in migraine pathophysiology and exhibits high sensitivity to neuronal excitation." (PMID 39009958, 2024). "While IL-1β has a well-identified role in migraine pathogenesis, CXCL1 and CCL2 are associated with pain hypersensitivity and more recently with migraine." (PMID 36359895, 2022). "According to previous clinical research, a high level of MCP-1/CCL2 was observed in the serum of patients with migraine; moreover, CCR2 was also associated with migraine." (PMID 37450927, 2024). "Our study indicates that R192Q KI trigeminal ganglia had higher mRNA and protein levels of the macrophage-related chemokine MCP-1/CCL2 involved in macrophage recruitment/mobility and activation and also found raised in the plasma of migraine patients." (PMID 23326332, 2013). "Cerebrospinal fluid (CSF) from patients with migraine or tension-type headache contained significantly higher levels of CCL2 in comparison with healthy controls, suggesting a relationship between headache and CCL2 expression." (PMID 35295531, 2021). "Rapid upregulation of Ccl2 mRNA after a single CSD has been shown in the cortical parenchyma of anesthetized mice as well as in the dura mater and trigeminal ganglion tissues in the nitroglycerin model of migraine." (PMID 39009958, 2024).
nonalcoholic steatohepatitis (19 papers, 2014 to 2025). "Consistent with the results of this study, previous studies found that CCL2 signaling was associated with metabolic disorders during the development of non-alcoholic steatohepatitis and contributed to the lipid accumulation in hepatocytes." (PMID 33042108, 2020). "Indeed, elevation of hepatic CCL2 following liver damage has previously been demonstrated in alcoholic liver disease, non-alcoholic steatohepatitis, and in acute liver failure." (PMID 25012628, 2014). "Conversely, METTL3 knockdown increased the free fatty acid uptake mediated by CD36, and the inflammation reaction induced by C-C motif chemokine ligand 2 (CCL2), as the result, lead to the progression from NAFLD to non-alcoholic steatohepatitis (NASH)." (PMID 36157445, 2022).
pancreatitis (19 papers, 2012 to 2024). Inflammation of the pancreas. "Our study identified an increase in Ccl2 when pancreatitis was induced in mice with reduced pancreatic OGT; this result is consistent with this previous work in the context of vascular injury." (PMID 35336721, 2022). "For example, CCL2 produced by acinar cells leads to the development of pancreatitis via migration of CCR2-expressing myeloid cells into the pancreas." (PMID 29891873, 2018). "To determine whether these interactions were in fact necessary for the development of pancreatitis, we first assessed the effect of neutralizing Ab against CCL2 or CCL25 administered at the time of poly(I:C) administration." (PMID 39264798, 2024). "Similarly, levels of the monocyte chemoattractant CCL2 were significantly elevated 9 hours after pancreatitis induction in both pancreas and lungs." (PMID 23110041, 2012). "Elevated levels of serum cytokines and chemokines including IL-6, CCL2, and CXCL1 have been reported to be pathological hallmarks of pancreatitis after CVB3 infection." (PMID 27195463, 2016). "Following induction of pancreatitis with cerulein, levels of pancreatic IL-1β, IL-6, CCL2/MCP-1, and neutrophil infiltration were much greater in ob/ob and db/db mice compared to their lean littermates." (PMID 24474939, 2013).